MMP2 (matrix metallopeptidase 2)
Diseases named in the same sentence as MMP2 in open-access papers (continued):
Sharing a sentence is not in itself a finding about the gene and the disease.
cancer (continued). "Sub-toxic concentration of 3-azidowithaferin A (3-azido WA) inhibited cancer cell motility and invasion in wound healing and Boyden chamber invasion by suppressing MMP-2 activity in gelatin zymography and its expression has proved to be a major obstacle in chemo-sensitivity." (PMID 22962598, 2012). "Type IV collagenases MMP-2 and -9 have been the focus of research as type IV collagen is a major structural protein for ECM and basement membrane, and MMP-2 and -9 expression is associated with cancer cell invasion and elevated in a variety of malignancies." (PMID 23226724, 2012). "Moreover, FAK promotes the expression of MMP2 and 9 through the Src-mediated signaling cascade and induces activation of cell survival signals as well as the secretion of MMPs into the matrix in cancer cells." (PMID 23320038, 2012). "Among these MMPs, MMP-2 and MMP-9 are directly linked with angiogenesis and degradation of the basement membrane collagen, and their expression and activity are correlated with metastatic abilities and prognosis of cancer." (PMID 23006512, 2012). "Berberine also showed anti-metastatic properties in several cancer cell lines, acting on 72 kDa type IV collagenase (MMP2), Cdc42 effector protein 1 (CDC42EP1), and ras-related C3 botulinum toxin substrate 1 (RAC1), transforming protein RhoA (RHOA) and urokinase-plasminogen activator A (PLAU)." (PMID 23213296, 2012). "MT1-MMP was distributed similarly to MMP-2 in malignant tumors and was reduced in benign tumors." (PMID 21726449, 2011). "Matrix metalloproteinase-2 (MMP-2) plays an important role in cancer progression and metastasis." (PMID 21969874, 2011). "MMP-9 and MMP-2 play critical roles in the degradation of type IV collagen, a major constituent of the basement membrane, and are closely related to the invasion and metastasis of various cancer cells." (PMID 21738655, 2011). "Given the important role of Runx2 in cancer-induced angiogenesis and metastasis, we wondered whether it plays a role in the inhibition of MMP-2 and MMP-9 expression induced by LGD1069." (PMID 21649908, 2011). "However, a reduction of cancer cell invasiveness and MMP-2 released from the MDA-MB-231 cells were observed at a concentration of 1000 pg ml–1 PGE2." (PMID 21792195, 2011). "Interestingly, immunohistochemistry showed an intense reaction for the stromal fibroblast component, with a significant increase in MMP-2 (p = 0.05) and MT1-MMP (p = 0.001) expression in the fibroblasts associated with carcinoma." (PMID 21726449, 2011). "In the simple carcinomas, the MMP-2 activity ranged between 47.4 and 87.5 units." (PMID 21726449, 2011). "Firstly, THL could inhibit, in cancer cells, the expression and secretion of MMP-2, MMP-9, and uPA, which involve in degradation of extracellular matrix and play important roles in cancer cell migration and invasion." (PMID 20429953, 2010). "Like the related invadopodia described in other cancer cells, the podosomes are actin-rich structures closely associated with adhesion molecules and ECM-degrading enzymes such as the matrix metalloproteinases MMP-1, MMP-2 or MMP-9." (PMID 20152043, 2010). "Therefore if MMP-2 is high, cancer cells can easily invade surrounding tissue, since basement membranes and extracellular matrices are destroyed." (PMID 19671184, 2009). "CAS overexpression enhanced matrix metalloproteinase-2 (MMP-2) secretion and cancer cell invasion." (PMID 18597698, 2008). "The extent to which MMP-2 contributes to FAK-mediated cell invasion in other cancer cells remains unknown." (PMID 18349846, 2008). "Furthermore, it has been reported that PKC isoforms influence the morphology of the actin cytoskeleton, as well as the activation of metalloproteases MT1-MMP and MMP-2, reported to be involved in cancer cell migration." (PMID 18294404, 2008). "MMP-2 and MMP-9 are proteinases implicated in cancer progression." (PMID 18506186, 2008).
cancer (continued). "The ability of spheroids to contribute to the spread of cancer has been assessed by growth, adherence and disaggregation capabilities and by investigating the profile of integrins and MMP2/MMP9 that may mediate the dissemination process." (PMID 17567918, 2007). "Inhibition of migration, invasion, and motility was consistent with decreased activities of the matrix metalloproteinase-2 (MMP-2) and the urokinase-type plasminogen activator; two highly involved enzymes associated with degradation of the extracellular matrix and promoting cancer dissemination." (PMID 41585866, 2025). "Furthermore, CAF-derived PDGFC promotes epithelial-mesenchymal transition (EMT) in cancer cells as well as matrix metalloproteinase 2 (MMP2) expression through the PDGF receptor A (PDGFRA)-mitogen-activated protein kinase/extracellular signal-regulated kinase (MAPK/ERK) pathway." (PMID 40501228, 2025). "Furthermore, hydnocarpin markedly decreased the expression levels of cancer-promoting factors, including matrix metalloproteinase (MMP)-2/9, C–C motif chemokine ligand 5, transforming growth factor-β, and vascular endothelial growth factor, which were upregulated in OC-MQs." (PMID 40722951, 2025). "We integrated analyzed the function of P4HA3 among 33 types of cancers, and found that P4HA3 was associated with proliferation markers (PCNA and MKI67), EMT markers (VIM, TWIST1, SNAI1, SNAI2, FN1 and CDH2), extracellular matrix (ECM) markers (MMP9, MMP7, MMP2 and MMP14)." (PMID 39504328, 2024). "In addition, resveratrol also modulated some cellular signaling pathways, such as Akt or c-Jun N-terminal kinases; this could be responsible for suppressing MMP-2 and weakening cancer cell motility, adhesion, and invasion." (PMID 39335164, 2024). "Moreover, calycosin inhibited the proliferation, invasion, and migration of cancer cells through decreasing MMP‐2, MMP‐9, and CD147 levels through downregulating BATF (basic leucine zipper ATF‐like transcription factor) expression and TGFβ1 (transforming growth factor 1) expression." (PMID 38230908, 2024). "Therefore, MMP-2 inhibition tends to be a target for tissue repair and cancer metastasis." (PMID 37513440, 2023). "Thus, MMP-2, chloride channels, and Annexin 2 are all involved in malignant cell migration and invasion and provide therapeutic opportunities for targeting GB and NB cancers." (PMID 37444498, 2023). "Only upon interaction with both MMP-2 and cathepsinB, either in a buffer solution or in cancer cells, both of the segmentswere cleaved specifically, and the two components could be completelyseparated, thereby restoring the photodynamic activities of the DSBDPmoiety." (PMID 36961946, 2023). "Therefore, the NF-kB-mediated expression of MMP-2 and -9, respectively, are the most important driving force in the invasiveness and metastasis of various human cancers such as colorectal cancer, hepatocellular cancer, nasopharyngeal carcinoma, and non-small cell lung cancer." (PMID 36993955, 2023). "However, the role of ADAMDEC1 and MMP2 in cancer is still unclear." (PMID 36172139, 2022). "In addition, MN decreased cancer cell migration via reduction in MMP-2 and -9." (PMID 35164236, 2022). "In addition, decorin, which is expressed in the stroma of various cancers and can be cleaved by MMP2, 3, 7 and MT1-MMP, recognizes and binds to all isoforms of TGF-β to form an inactive complex, which inhibits TGF-β signaling in vitro and indirectly attenuates downstream signaling pathways." (PMID 36591235, 2022). "The gelatinase protein family including MMP2 (gelatinase A) and MMP9 (gelatinase B) are able to degrade type IV collagen in basement membranes and are the most extensively studied metalloproteinases that are associated with disease progression and poorer survival in patients with various cancers." (PMID 36591235, 2022).
cancer (continued). "Since we observed an impact of altered zinc homeostasis upon the surface expression and phosphorylation of the EGFR, we investigated whether the altered zinc homeostasis also affects the expression of the EGFR-regulated, cancer-relevant proteins E-cadherin, MMP-2 and PD-L1." (PMID 35216384, 2022). "Regarding the onset of cancer, LOX-1 was shown to be upregulated in different tumors and has been linked to their progression and metastasis through the upregulation of VEGF, the activation of HIF-1alpha, and the induction MMP-9/MMP-2, subsequently leading to neo-angiogenesis." (PMID 35269979, 2022). "Thus, after disassembly, DOX-KGFRWR has synergistic effects in anti-tumor therapy; it binds with the extracellular enzyme MMP-2 to inhibit the migration of cancer cells, and it also crosses the cell membrane via endocytosis and enters the nucleus to downregulate cancer cell mitosis." (PMID 35057106, 2022). "Furthermore, the potential migration and invasion inhibitions by the ethanolic extract of the Egyptian B. nigra was also evidenced by the downregulation of MMP2, MMP9, and Snail genes, and the upregulation of the E-cadherin gene (hallmark of cancer metastasis)." (PMID 35956938, 2022). "Finally, silencing of TSPAN14 in these non-metastatic cancer cells caused an increased expression of matrix-degrading enzymes MMP-2 and MMP-9, followed by an elevated capacity of cancer cells to degrade gelatin." (PMID 36143328, 2022). "In addition, exosomes could activate MMP-2 to enhance the invasiveness required for the first step in the metastasis of cancer cells." (PMID 36230852, 2022). "Moreover, the complexity of the MMP2 role in cancer should be mentioned here, since MMP2 may be involved in blocking angiogenesis by cleaving plasminogen and producing angiostatin." (PMID 35406617, 2022). "Hence, many studies have focused on the effects of MMP-2 on cancer invasion and migration." (PMID 35205628, 2022). "Besides VEGFA, the inhibition of miR-29b could upregulate the expression of other oncoproteins, such as DNMT3b, LOXL2, and MMP2 in some cancers." (PMID 34306080, 2021). "Therefore, it is suggested that C1 being novel chemically may also possess novel bioactivities by being a specific target for PEX-domain of MMP2, to possibly inhibit a panel of cancer cells as well." (PMID 34075089, 2021). "CircPUM1 up-regulated the expression of nuclear factor kappa B (NF-κB) and MMP2 by sponging miR-615-5p and miR-6753-5p to promote ovarian cancer proliferation, migration and invasion, which also acts on the peritoneum and contributes to metastasis of cancer in the form of cancer-derived exosomes." (PMID 32935262, 2021). "Thus, for the first time, differences in the levels of 20S proteasomes, ADAM10+/ADAM17-, MMP9+ and MMP9+/MMP2+/EMMPRIN+ in plasma exosomes subpopulations between CPPs and CRCPs were revealed, thereby indicating the feasibility of using them to predict cancer risk." (PMID 33773551, 2021). "Therefore, the stronger inhibition of these features in this cell line could be correlated with a reversion of abnormal pHe in cancer cells and the consequent lower activity of MMPs, namely MMP-2." (PMID 33572458, 2021). "Additionally, the same research group analyzed whether there was a correlation between Nucb2-regulated cell migration and the significance of Nucb2 in the migration of cancer cells facilitated by the action of matrix metalloproteases MMP-2 and MMP-9." (PMID 34073612, 2021). "The results obtained demonstrate that CHPF is highly expressed in BRCA, and may act as a cancer promoter to increase cell viability and invasiveness by regulating matrix metallopeptidase 2 (MMP2) expression and epithelial‐mesenchymal transition (EMT)‐related proteins." (PMID 33301643, 2021).
cancer (continued). "In cancer cells, members of the MAPK family, including MEK/ERK, p38, and c-Jun N-terminal kinase (JNK), are phosphorylated and translocated from the cytoplasm to the nucleus to activate cell proliferation and regulate various downstream substrates, including MMP-2, MMP-9, and EMT-associated genes." (PMID 34733776, 2021). "Therefore, MMP2 from the stromal cells may affect cancer progression in a paracrine manner, even though at the early stage cancer cells are separated from stromal cells by the basement membrane." (PMID 33178597, 2020). "Thus, MMP-2 targeting should be re-considered as an effective strategy to halt cancer progression." (PMID 33321813, 2020). "TIMP-3 downregulation is related to cancer invasion and metastasis in various cancers; however, higher serum level of TIMP-1 is associated with lower response to therapy in breast cancer patients, and TIMP-1 has been used as a biomarker along with MMP-2 and ICAM-1 for pancreatic cancer." (PMID 32466129, 2020). "In addition, activated MMP-2 and MMP-9 is associated VEGF bioavailability in cancer." (PMID 32353975, 2020). "MMP-2 can break the degradation balance of matrix, induce cancer cells to penetrate the barrier formed by extracellular matrix and basement membrane, and reduce the adhesion between cells, so that cancer cells can infiltrate, invade, and metastasize to distant organs in surrounding tissues." (PMID 32184893, 2020). "In addition, the dual role of TIMP-2 (as the main inhibitor of MMP-2) in cancer is demonstrated." (PMID 32751899, 2020). "While in middle stage LSCC, MMP2 is upregulated by the regulation of TF JunB in the aberrance of miR-106b and is also affected by DNA methylation, suggesting that the dysfunction of miR-106b can cause the abnormal ECM degradation to potentially promote the invasion and metastasis of cancer cells." (PMID 31217907, 2019). "Furthermore, some studies investigated the effect of blocking MMP-2 expression on cancer invasion." (PMID 31582999, 2019). "Furthermore, the migration of cancer cells across tissue involves the focal proteolysis of the ECM components at the invasive edge of the migrating cells, which is mediated by cell surface‐associated enzymes such as MMP‐2." (PMID 30637950, 2019). "Furthermore, MMP-2 and MMP-9 were closely associated with the poor outcome of cancer patients." (PMID 30931081, 2019). "Therefore, MMP-9 and MMP-2 could be CoQ0-responsive mediators whose ECM degradation could result in ensuing cancer invasion and migration." (PMID 31068208, 2019). "In our study, MMP-9 was associated with cancer pain, but MMP-2 was not." (PMID 31239855, 2019). "Hence, the inhibition of MMP-2 mediated invasion could be an important feature for cancer prevention." (PMID 31660294, 2019). "Furthermore, cancer metastasis-indicators MMP2 and MMP9 proteins were down-regulated." (PMID 32083017, 2019). "Given that MMP-2 inhibition can re-open the P2RX7 LP in cancer cells and effectively switch on the LP-associated cell death pathway, it might be possible to develop a new generation of cancer therapeutics promoting this P2RX7 LP formation." (PMID 30003075, 2018). "EVs carry molecules such as CD24, and epithelial cell adhesion molecule (EPCAM1), which directly regulate cancer-cell migration, proteases (MMP2, MMP9), which promote ECM degradation and cancer invasiveness, or EV-associated mRNAs, such as miR21, which may induce resistance to paclitaxel." (PMID 30200478, 2018). "Additionally, elevation of miR-149 restrained the expression of MMP-9 and MMP-2 in cancer cells." (PMID 30126849, 2018). "Osteoclast activity in the endosteal niche may contribute to the awakening of dormant cancer cells as a result of increased bone remodeling, with resultant high levels of bioavailable TGFβ1 isoform, generated in part by MMP-2, contributing to micrometastatic outgrowth." (PMID 29874869, 2018). "Hence Pimozide may prevent the migration of cancer cells at least in part through the down-regulation of MMP2." (PMID 30405882, 2018).
cancer (continued). "Notably, the cross-talks between cancer cells and PSCs may result in further remodelling of the stromal microenvironment via activity of MMP-2." (PMID 28382480, 2017). "However, the mechanisms underlying overexpressed RhoGDIβ leading to mmp‐2 transcription and cancer invasion of human BC have never been explored." (PMID 28846829, 2017). "Moreover, artemisinin reduces cancer cell migration and invasion by reducing the expression of matrix metalloprotease (MMP)-2 and MMP-9 and increases the cells’ adhesive ability by enhancing the expression of E-cadherin, resulting in the downregulation of cancer metastasis." (PMID 28737711, 2017). "Therefore, according to the results of the present study, BM-MSC behavior may resemble those of cancer cells with respect to augmenting cellular invasiveness via MMP-2 activation under hypoxia." (PMID 26880989, 2016). "There is evidence that VEGF promotes the secretion of some enzymes that facilitate the metastasis of cancers, and that overexpression of VEGF can induce MMP-2 and MMP-9, which may be a major mechanism underlying the invasion and metastasis of highly invasive cancers." (PMID 27153056, 2016). "Therefore, targeting of MMP-2 and -9 represents a promising strategy for cancer treatment." (PMID 27733866, 2016). "Furthermore, both Metformin and Ara-a had an inhibitory effect on the invasive ability of both glial and neuronal cancer cells, possibly through decreasing MMP-2 production that is known to have a role in cancer progression by aiding extracellular matrix degradation." (PMID 26635517, 2015). "Therefore, scutellarein may further decrease the expression of MMP-2, -9 and -14 through the NF-κB signaling pathway, thus inhibiting the migration and invasion of cancer cells." (PMID 25394920, 2015). "Moreover, the intensity of MMP-2 expression in inflammatory cells correlated significantly with the expression of this protein in cancer cells (p = 0.006) and with the expression of TIMP-2 in all types of cells analyzed (p = 0.040, p = 0.003, and p = 0.0495, respectively)." (PMID 24395652, 2014). "Additionally, integrin expression plays role in activation of MMP-2: interaction of MMP-2 with αvβ3 integrin is required during its maturation and activation demonstrating localization of active MMP-2 and αvβ3 integrin at the migration front accelerates cancer cell migration." (PMID 25302298, 2014). "In conclusion, MMP2 expression may be regulated by HIF-1α in HCC, and the hypoxic microenvironment in HCC tissues may induce nuclear transcription factor HIF-1α overexpression, which possibly activates MMP2 and participates in the invasion and metastasis of the cancer cells." (PMID 25013467, 2014). "TGF-β1 may enhance the ability of MMP2/9 in resorbing bone and favouring invasion of cancer cells." (PMID 23378237, 2013). "Moreover, at the molecular level, inhibition of Dicer in human cancer U251, MCF-7 and SCG7901 cell lines enhanced the expression of cell cycle-associating molecules cyclin A and PCNA, as well as invasion-promoting factors MMP-2 and MMP-9." (PMID 23599754, 2013). "Furthermore, MMP2 selects more aggressive phenotypes by generating apoptosis-resistant cells via the cleavage of proapoptotic factors, in addition to collaborating with other MMPs to promote cancer-related angiogenesis." (PMID 24223658, 2013). "Therefore, the inhibition of MMP-2 or MMP-9-mediated migration or invasion may be a preventive method of limiting cancer metastasis." (PMID 24053256, 2013). "Moreover, syntenin overexpression did not alter the expression of matrix metalloproteinases such as MMP-2 and -9, or their proteolytic activities, as assessed by gelatin zymography, which supports that syntenin promotes metastasis of cancer cells mainly through increasing their migratory activity." (PMID 23786877, 2013).